Y_RNA (Y RNA )
Gene: Miscellaneous RNA gene on chromosome 2 (174,264,878 to 174,264,981, reverse strand). Ensembl gene ENSG00000201088.
Homologues: Orthologues: chimpanzee Y_RNA (100% identical), macaque Y_RNA (97% identical). Paralogues in human: Y_RNA (88% identical), RNY3 (87% identical), Y_RNA (87% identical), Y_RNA (86% identical), Y_RNA (85% identical), RNY3P1 (84% identical), Y_RNA (84% identical), RNY3P14 (83% identical), RNY3P2 (83% identical), Y_RNA (83% identical), RNY3P16 (82% identical), RNY3P4 (82% identical), and 97 more.